ZBTB3 (zinc finger and BTB domain containing 3)
Description:
May be involved in transcriptional regulation.
Synonyms: FLJ23392
Tractability: PROTAC: UniProt records ubiquitination sites on it.
Gene: Protein-coding gene on chromosome 11 (62,748,319 to 62,758,835, reverse strand). Ensembl gene ENSG00000185670.
Subcellular location: Nucleus
Subcellular location (Human Protein Atlas): Mitochondria
Gene Ontology:
Molecular function: protein binding; DNA-binding transcription factor activity, RNA polymerase II-specific
Biological process: regulation of transcription by RNA polymerase II
Cellular component: nucleus
Genetic constraint (gnomAD): Loss-of-function variants: 15 observed, 31.98 expected, observed/expected ratio (o/e) 0.47, 90% interval 0.31 to 0.72. The upper end of that interval is the gene's LOEUF score, 0.72, which puts it in group 2 of 6, group 1 being the genes least tolerant of losing a copy. Missense variants: 599 observed, 689.52 expected, observed/expected ratio (o/e) 0.87, 90% interval 0.81 to 0.93. Synonymous variants: 258 observed, 277.14 expected, observed/expected ratio (o/e) 0.93, 90% interval 0.84 to 1.03.
Homologues: Orthologues: chimpanzee ZBTB3 (99% identical), macaque ZBTB3 (94% identical), rabbit ZBTB3 (89% identical), dog ZBTB3 (87% identical), rat Zbtb3 (83% identical), mouse Zbtb3 (83% identical), guinea pig ZBTB3 (77% identical), zebrafish zbtb3 (38% identical), tropical clawed frog zbtb3 (37% identical). Paralogues in human: BCL6 (21% identical), BCL6B (20% identical), ZBTB46 (18% identical), ZBTB49 (16% identical), ZBTB7B (14% identical), ZBTB21 (14% identical), ZBTB33 (13% identical), NACC1 (13% identical), ZBTB12 (13% identical), NACC2 (12% identical), ZBTB14 (12% identical), ZBTB25 (12% identical), and 16 more.
Diseases named in the same sentence as ZBTB3 in open-access papers:
ZBTB3 is named in the same sentence as 9 diseases in open-access papers, as found by Europe PMC text mining. Sharing a sentence is not in itself a finding about the gene and the disease. The quoted sentences say what the papers report.
autoimmune disease (1 paper, 2023). A disorder resulting from loss of function or tissue destruction of an organ or multiple organs, arising from humoral or cellular immune responses of the individual to their own tissue constituents. "Here the authors used an evidence-based strategy to prioritize causal pleiotropic variants of autoimmune diseases, and revealed that rs4728142 modulates aberrant IRF5 alternative promoter usage by ZBTB3-mediated chromatin looping." (PMID 36869052, 2023).
depression (1 paper, 2016). "Taken together, when rs1863918 SNP is T allele, it is assumed that ZBTB3 plays a direct role in these processes by binding to the target region or has an indirect role by upregulating ZNF354C expression in the hippocampus as the onset mechanism of depression." (PMID 27723809, 2016).
endometrial cancer (1 paper, 2025). Primary or metastatic malignant neoplasm involving the endometrium (mucous membrane that lines the endometrial cavity). "However, endometrial cancer -associated SPOP mutants exhibit impaired regulation of ZBTB3 stability." (PMID 40521202, 2025). "Notably, ZBTB3 regulates the transcription of sonic hedgehog (SHH), with SPOP inactivation leading to ZBTB3-dependent SHH upregulation in endometrial cancer cells." (PMID 40521202, 2025).
cancer (5 papers, 2016 to 2025). A tumor composed of atypical neoplastic, often pleomorphic cells that invade other tissues. "Among them, ZBTB3 has emerged as a critical regulator of cancer cell proliferation via the reactive oxygen species (ROS) detoxification pathway." (PMID 40521202, 2025). "ZBTB3 is an essential factor for cancer cell growth via the regulation of the ROS detoxification pathway." (PMID 29348864, 2017). "This is interesting since ZBTB3 is known as a structural regulator of enhancer-promoter interactions where it co-activates genes to modulate the self-renewal of embryonic stem cells and the proliferation of cancer cells." (PMID 38994563, 2024). "It has been reported that ZBTB3 is a transcription regulatory factor that either activates or suppresses transcription according to the cellular context and which is essential for the proliferation of cancer cells." (PMID 27723809, 2016). "Importantly, by targeting the downstream effects of SPOP loss—particularly the accumulation of ZBTB3 and its upregulation of SHH—these therapies could address the unique oncogenic mechanisms in SPOP-mutant cancers, potentially improving patient outcomes with reduced off-target effects." (PMID 40521202, 2025).
tumor (1 paper, 2017). "The involvement of FEN1, ZBTB3, and MTA2 in controlling genomic stability suggests that functional dysregulation of these genes through mutations would facilitate further tumor mutagenesis, raising the possibility of these oncogenes as potential therapeutic targets for ESCC patients." (PMID 29348864, 2017).
ZBTB3 also shares sentences with these, for which no sentence is quoted: breast carcinoma (1 paper); infection (1); lung carcinoma (1); melanoma (1).